CDC25A (cell division cycle 25A)
Diseases named in the same sentence as CDC25A in open-access papers (continued):
Sharing a sentence is not in itself a finding about the gene and the disease.
cancer (continued). "CDC25A is a protein phosphatase key regulator of the cell-cycle that is overproduced in many human cancers." (PMID 30036966, 2018). "MiR‐365 plays roles in the initiation and development of cancers by repressing bcl‐2 and cyclin D1/cdc25A expression." (PMID 29451327, 2018). "We further evaluated the effect of BRE knockdown on CDC25A degradation in other human cancer cell lines." (PMID 29416040, 2018). "In cell cycle analysis, DPS-2 induced S phase delay 48 h after treatment while cdc25A degradation was detected through Western blotting at 72 h in both cancer cell lines." (PMID 31105235, 2018). "More importantly, overexpression of Cdc25A has been frequently observed in multiple types of tumors, which is correlated to the poor prognosis in cancer patients." (PMID 28680535, 2017). "However, the detailed mechanism underlying CDC25A overexpression in cancer cells is still unknown." (PMID 28333141, 2017). "A key regulator of G1-S and G2-M transitions, CDC25a is overexpressed in human cancers driving abnormal cell proliferation downstream of multiple signaling pathways including STAT3." (PMID 28222105, 2017). "So far, the main mechanisms by which Roc-A inhibits cancer cell proliferation have been shown to be due to inhibition of protein synthesis initiation and induction of Cdc25A degradation by activation of the ATM/ATR check point pathway." (PMID 27340868, 2016). "The activity and abundance of Cdc25A are intricately regulated and Cdc25A is frequently overexpressed in several cancer types." (PMID 26967250, 2016). "At present, high CDC25a expression has been reported in a variety of cancer cell lines or tumor tissues and has also related with tumorigenesis and poor prognosis." (PMID 27384875, 2016). "The finding that Cdc25A upregulates itself in a positive feedback mechanism via dephosphorylation of PKM2 and upregulation of c-Myc provides an instrumental insight into the role of overexpression of Cdc25A in cancer development." (PMID 27485204, 2016). "Here we showed that the expression of CDC25a had close relationship with the expression of YBX1 in cancer tissues samples on the basis of novel adenocarcinoma subtypes classification by immunohistochemical staining for the first time." (PMID 27384875, 2016). "This study provides new and revealing results that support the importance of Cdc25A acetylation in response to genotoxic stress and in cancer." (PMID 26967250, 2016). "Common feature of all tested fibrates are changes in expression of Cdc25A and cyclin E in all three tested cell lines and cyclin A in carcinoma-derivated cell lines HepG2 and HT-29." (PMID 27658584, 2016). "Deletion of CDC25A has also been reported (cancer genome project database) in varying frequencies in numerous human cancer." (PMID 23675485, 2013). "It was previously shown that members of this family simultaneously inhibit multiple oncogenic pathways in cancer cells regulating the expression of relevant oncogenes like cmyc, ras, CDC25A, and HMGA2 among others." (PMID 23798998, 2013). "A paradigmatic example is represented by the cell division cycle 25A (Cdc25A) protein, which is often found expressed in high concentration in many cancers." (PMID 24349068, 2013). "Differential expression (RNA/protein) pattern of CDC25A (30–80%) has been reported in different carcinomas in liver, esophagus, colon, breast including head and neck." (PMID 23675485, 2013). "For example, Cdc25a, Cdc25b and Cdc25c, members of the Cdc25 family, are significantly co-expressed (p < 10-6) with the cancer-related genes." (PMID 23039964, 2012). "Though CDC25A has been extensively studied for its role in tumor progression and as a potential target for cancer treatment, the mechanisms of CDC25A overexpression in cancer remains to be investigated." (PMID 23071577, 2012).
cancer (continued). "The importance of its tight regulation is underscored by the observation that defects in maintaining steady state levels of Cdc25A translate into increased cell proliferation that can lead to cancer." (PMID 21310058, 2011). "The Cancer Pathway Finder Array analysis identified numerous cancer-associated genes exhibiting substantial over expression in trisomic BG01V APCs relative to diploid H9 APCs, including CDC25A, IGF1, MMP9, FGFR2, BRCA1, CASP8 and TERT1." (PMID 20423517, 2010). "In this study, therefore, we investigated the expression of cdc25A and cdc25B in order to elucidate the role of these proteins as modulators of the cell cycle progression of this carcinoma." (PMID 12085185, 2002). "The clinical significance of cdc25A in carcinoma also seems to vary, because different results have been reported for carcinomas of different origin." (PMID 12085185, 2002). "Interestingly, miR-449a targets CDC25A and its expression is repressed in cancer cells and it is known to have tumor suppressor functions." (PMID 39173945, 2024). "CDC25A significantly increased the cholesterol metabolism through endosome pathway in quiescent cancer cells, leading to the significant changes in cytoskeleton and membrane properties so as to enhance the resistance of mechanical force in circulatory system, facilitating lung metastasis." (PMID 39390252, 2024). "In summary, we established a quiescent model and demonstrated that whether CDC25A regulates cholesterol levels in quiescent cancer cells, thereby augmenting their resistance to chemotherapy and mechanical forces and facilitation of their metastatic potential." (PMID 39390252, 2024). "Overexpression of CDC25A has been reported in various human cancer tissues." (PMID 36717077, 2023). "The genes associated with microRNA in cancer included PTEN, CDC25A, SPY2, PLAU, E2F2, and PTGS2." (PMID 36077151, 2022). "To gain insights into the mechanisms of carcinogenesis-related USP29 activity, we investigated whether USP29 can modulate Cdc25A oncogenic functions in cancer cells." (PMID 34071237, 2021). "Thus, our results indicated that USP29 played a crucial role in regulating Cdc25A stability for proper cell cycle progression and prevented apoptosis in cancer cell lines." (PMID 34071237, 2021). "Thus, Cdc25A is a potential candidate protein contributing to progression of tumors by regulating the cancer cell cycle." (PMID 34071237, 2021). "Likewise, overexpression of Cdc25A in various cancers disrupts the cell cycle and results in tumorigenesis and genomic instability, while inhibition of Cdc25A leads to cancer cell apoptosis." (PMID 34071237, 2021). "In normal cells, Cdc25A expression is regulated tightly, but the changes in expression patterns in cancer cells that lead to tumorigenesis are unknown." (PMID 34071237, 2021). "Importantly, preclinical studies have validated WEE1 inhibition as a viable therapeutic target in treating cancer, and CDC25A is also deemed as a suitable therapeutic target for cancer treatment, establishing βTrCP as a tumor suppressor." (PMID 33130827, 2021). "Furthermore, knockdown of ErbB2 in Cdc25A-transfected cells inhibited the increased viability mediated by Cdc25A overexpression in sorafenib-treated cancer cells." (PMID 34743185, 2021). "Additionally, Cell Division Cycle 25A (CDC25A), a gene involved in cell cycle regulation in cancer was a DEG for geldanamycin." (PMID 33413081, 2021). "Aberrant expression of Cdc25A has been observed in many cancers." (PMID 34743185, 2021). "Silencing CDC25A or treatment with CDC25A inhibitor could reverse the B7-H3-induced chemoresistance of cancer cells." (PMID 32127943, 2020). "Upon DNA damage, ATR-Chk1 cascade is activated, and then sequesters Cdc25A in the cytoplasm where it cannot de-phosphorylate and activate Cdk1/Cyclin B7,8, or degrade Cdc25A via the SCFβTrcp 9–12, which is fundamentally crucial for cancer development." (PMID 32351703, 2020).
cancer (continued). "It has been reported that CDC25A could assist both G1/S and G2/M progression in various types of cancers." (PMID 32127943, 2020). "This role may be synergistic with CDC25A, because elevated CDC25A levels in human cancer correlated positively with USP17 activity, and USP17 was shown to cooperate with H-RAS to transform NIH3T3 cells." (PMID 30854565, 2019). "Whereas it was unclear how cdc25a expression is activated in these early embryos, our studies point to Stat3 as a regulator of cdc25a during zebrafish development, paralleling this role in cancer." (PMID 28222105, 2017). "Although much regarding Cdc25A acetylation remains unresolved, our data provide new mechanistic insights into the role of Cdc25A acetylation in cell cycle regulation following genomic insult and in cancer." (PMID 26967250, 2016). "This notion would be consistent with Cdc25A dysregulation seen in several cancer types." (PMID 26967250, 2016). "Overexpression of Cdc25A phosphatase is often observed in cancer and results in poor prognosis." (PMID 27658584, 2016). "Given that Cdc25 has been targeted for cancer therapy, these findings may lead to an alternative approach involving intervention in Cdc25A function for the treatment of human cancers." (PMID 27485204, 2016). "Alternatively, loss of function or dysregulation of ARD1 and HDAC11 that disrupt steady state Cdc25A acetylation might also explain aberrant Cdc25A levels in those cancers." (PMID 26967250, 2016). "While expression of Cdc25A, ARD1, and HDAC11 is deregulated in several types of cancers, the mechanism underlying this dysregulation remains unclear." (PMID 26967250, 2016). "Cdc25A overexpression has been detected in many types of cancer and correlates with poor prognosis." (PMID 27485204, 2016). "For example, stabilization of Cdc25A by the acetylation pathway may be responsible, in part, for a subset of cancers where ARD1 is overexpressed or HDAC11 is mutant resulting in elevated levels of Cdc25A." (PMID 26967250, 2016). "While recent literature indicates Dub3 as an eligible therapeutic target for cancers expressing Cdc25a, our results imply that its inhibition may be ineffective in tumor initiating cells, which actually don't rely on Dub3 function." (PMID 24349068, 2013). "miR-21 has been observed to target directly cdc25a in human cancer cells." (PMID 24349068, 2013). "miR-503 induced G1 arrest by downregulating cdc25A in heterologous cancer cells." (PMID 23967867, 2013). "CDC25A is frequently overexpressed in cancers including NSCLC." (PMID 23071577, 2012). "The suppression of CDC25A may hinder the viability of K562 cancer cells and promote apoptosis." (PMID 41373559, 2025). "Additionally, CDC25A inhibitors are promising as therapeutic targets for cancer treatment." (PMID 41373559, 2025). "Although we could not identify a specific transcription factor that may be directly responsible for the downregulation of TTLL11 in cancer we found that there is a causal link between the increased expression of two oncogenes, CCNE1 and cdc25a, and the downregulation of TTLL11." (PMID 36414642, 2022). "Moreover, Cdc25A overexpression restored this binding in sorafenib-treated cancer cells." (PMID 34743185, 2021). "Moreover, Cdc25A overexpression restored ErbB2 levels in sorafenib-treated cancer cells." (PMID 34743185, 2021). "Moreover, cell cycle obstacles were accompanied by the overexpression of CDC25A in cancer tissues 43, indicating that CDC25A might regulate the cell cycle in the development and progression of tumors." (PMID 32127943, 2020). "Hence, Cdc25A has emerged as a potential target for cancer therapy." (PMID 28680535, 2017). "Moreover, Cdc25A and B are known to be overexpressed in a diverse array of human cancers, suggesting an important role of the Cdc25s in the development of uncontrolled cancer cell division." (PMID 26228523, 2015).
cancer (continued). "Interestingly, the model predicts that CDC25A knockout enhances senescence, an outcome that could lead to a relevant target for intervention in cancer." (PMID 25573782, 2014). "Indeed, Cdc25A is frequently overexpressed in multiple types of cancer." (PMID 21310058, 2011). "The augmented expression of TGFBR2, CDC25A, SMAD7, and RELA and downregulation of p27 are major events in cell proliferation and cancer invasion." (PMID 40761498, 2025). "The increased expression of TGFBR2, CDC25A, SMAD7, and RELA and downregulation of p27 are major events in cell proliferation and cancer invasion." (PMID 40755497, 2025). "More importantly, CDC25A expression was positively correlated with IGF2BP3 and METTL3 expression in most cancer types in TCGA datasets." (PMID 39247830, 2024). "We also verified the binding of FHL1 with CDC25A and CHK1 proteins, which reportedly interact with FHL1 in other cancer cells." (PMID 35142956, 2023). "To corroborate this result, we also evaluated the expression of CDC25A, CDK1 and CCNB1, the most important cell cycle regulatory proteins involved in cancer progression." (PMID 37504902, 2023). "Our data are also supported by several recent papers that performed RNA-sequencing of several cancer cell lines after IMP1 knockdown, and CDC25A was found to be significantly down-regulated in IMP1-silenced cell lines including Panc-1 cells." (PMID 37894350, 2023). "CDC25A is a nuclear phosphatase regulating several CDK family members to allow cell cycle progression and found to be frequently overexpressed in cancers." (PMID 35063803, 2022). "In agreement, the analysis of the expression levels of CDC25A and DYRK2 in different cancer types with available normal-tumor matched data identified the opposite behavior of both genes." (PMID 34363019, 2022). "Cell division cycle 25A (Cdc25A) is a phosphatase that promotes cell cycle progression by activating cyclin-dependent kinase (CDK), which has the potential to promote cancer." (PMID 36613989, 2022). "Previous analyses of gene expression profiles in several cancer cells also showed that selenium specifically downregulated CYCLIN A, CYCLIN D, CDC25A, CDK4, and other cell cycle-related genes to induce cell cycle arrest." (PMID 34094961, 2021). "The transcription factor c-Myc plays an important role in the regulation of cell cycle through modulating cell cycle controllers, such as CDC25A, CDK4, CDK6, Rb, and p-Rb in cancer cells." (PMID 33572615, 2021). "CDC25A is a member of the CDC25 phosphatases that govern key transitions between cell cycle phases, which are frequently overexpressed in cancers." (PMID 34266408, 2021). "Last, TTK, CDC25A, and ESPL1 showed higher expression in the late cancer stage and higher tumour grade." (PMID 33282948, 2020). "Clinical datasets and cancer genomic datasets from the cBioPortal website were analysed, and the results showed that in cases with TTK, CDC25A, and ESPL1 amplification, EC patients had worse survival outcomes." (PMID 33282948, 2020). "In accordance with their critical roles in cell cycle regulation, CDC25A and CDC25B have been shown to be involved in cancer progression." (PMID 33385163, 2020). "We analysed cancer genomic datasets from the UCSC Xena website and found that TTK, CDC25A, and ESPL1 were highly expressed in EC tissues compared with normal tissues." (PMID 33282948, 2020). "Yuning Song and colleagues previously reported a CDC25 inhibitor, CHEQ-2, that not only inhibited the catalytic dephosphorylation activity of CDC25A and CDC25B in vitro, but also down-regulated CDC25A and CDC25B levels in cancer cells." (PMID 31024841, 2019). "In pathway in cancer and cell cycle, Bcl2, VEGFA, PTEN, Jun, Fos, APC2 were up-regulated and Ccna2, Cdc25a, Mcm3, Mcm6, Ccnb2, Mcm5, Cdk1, Gadd45a, Myc were down-regulated in the MMQ tumor stem-like cells." (PMID 28163656, 2017).
cancer (continued). "Recent study indicated that CDC25A, a critical cell cycle gene, is responsive to cellular hypoxia in human cancer, and HIF-1α-Myc pathway is also involved in the hypoxic downregulation of CDC25A." (PMID 29088751, 2017). "Reports have indicated that let-7 inhibits cancer cell proliferation by repressing multiple genes, including RAS, CDK6 and CDC25A." (PMID 28099144, 2017). "In HepG2 carcinoma cells, for example, STAT3 binds directly to CDC25a promoter and activates its expression." (PMID 28222105, 2017). "Our results revealed further cancer-relevant target genes including STAG2, CNOT6, SOX2, CDC25A and SFRS3." (PMID 23358700, 2013). "The aims of our study were to determine expression statuses of CDC25A, CDC25B and CDC25C in a large series of vulvar squamous cell carcinomas to shed light on their roles in the pathogenesis of this cancer type and to clarify their potential prognostic values." (PMID 20500813, 2010). "Consequently, CDC25A/CDC25B has emerged as a prominent target for the investigation and therapy of malignant neoplasms." (PMID 40076252, 2025). "In contrast, the expression levels of miR-122-5p diminish, implying that the overexpression of CDC25A and CDK4 may enhance the viability of these cancer cells and suppress apoptosis." (PMID 41373559, 2025). "In a silencing experiment, knockdown of CDC25A(△E6) but not CDC25A(L) drastically inhibited cancer-promoting characteristics." (PMID 36539837, 2022). "Overexpression of PKM2-S37D but not PKM2-WT suppressed Cdc25A-induced recovery in sorafenib-treated cancer cells." (PMID 34743185, 2021). "Lastly, TTK, CDC25A, and ESPL1 showed higher expression in cancers with late stage and higher tumour grade, which indicates that they may be potential targets for improving EC patient prognosis." (PMID 33282948, 2020). "TTK, CDC25A, and ESPL1 showed higher expression in cancers with late stage and higher tumour grade." (PMID 33282948, 2020). "Moreover, CHEK1 can directly phosphorylate CDC25A, thereby regulating the cell cycle and DNA damage response, indicating a potential role of DGUOK-AS1 in tumorigenesis and cancer progression." (PMID 32766141, 2020). "In addition, TTK, CDC25A, and ESPL1 showed higher expression in cancers with late stage and higher tumour grade, compared with early stage and lower tumour grade (P < 0.05)." (PMID 33282948, 2020). "Additionally, we uncovered the role of CDC25A in BRCA-mediated tumorigenesis, which can have implications in cancer treatment." (PMID 29416040, 2018). "It is therefore not surprising that Cdc25A and the proteins involved in its acetylation status are aberrantly expressed in several cancer types." (PMID 26967250, 2016). "Many cancers have been reported to overexpress CDC25A and CDC25B, but CDC25C has not previously been associated with cancer outcome." (PMID 27775025, 2016). "Since Cdc25A, ARD1, and HDAC11 are frequently dysregulated in multiple types of cancer, our findings may provide insight into a novel mechanism in carcinogenesis." (PMID 26967250, 2016). "However, miR-497 can also attenuate the malignancy of cancers by regulating other targets, such as TARBP2, DICER, BCL2, CCND1, CCNE1, CDC25A, CCND3, CDK4." (PMID 24667580, 2014).